TLR2 (toll like receptor 2)
Diseases named in the same sentence as TLR2 in open-access papers (continued):
Sharing a sentence is not in itself a finding about the gene and the disease.
Obesity (continued). "Since fatty acid concentrations are elevated in obesity, fatty acids could be the major endogenous ligands for TLR2 in adipose tissue." (PMID 19348674, 2009). "Because reduced expression of adiponectin receptors correlates with reduced AMPK activation, TLR2 activation may play an active role in the worsening insulin resistance in obesity." (PMID 19348674, 2009). "Since obesity is an inflammatory condition that is also associated with elevated TLR2 expression in adipose tissue, adipocyte TLR2 may indeed mediate part of the inflammatory environment that characterizes obesity." (PMID 19348674, 2009). "Nevertheless, the pattern of expression of TLR2 suggests that this receptor may be an important component of the inflammatory process in obesity." (PMID 19348674, 2009). "Thus, reduced TLR-2 or TLR-4 signalling proteins could protect them from obesity and obesity-related IR." (PMID 37036026, 2023). "The deletion of TLR2 might lead to obesity even if mice received a chow diet." (PMID 37383489, 2023). "Moreover, TLR2 and TLR9 deficiency promotes HFD-induced adiposity, visceral adipose inflammatory responses, and IR in mice, indicating that TLRs play a significant role in adipose tissue inflammation and IR in obesity." (PMID 37153549, 2023). "Our TLR2−/− mice displayed decreased glucose tolerance and increased circulating triglyceride levels, besides developing insulin resistance, which may be secondary to obesity." (PMID 36555322, 2022). "However, surprisingly, our observations demonstrated the opposite; TLR2-deficiency did not prevent prenatal LPS stimulation-induced obesity, and it instead promoted hyperlipidemia." (PMID 31507457, 2019). "Thus, we assessed the gene expression levels of the TLR2 and −4 in our diet-induced obesity (DIO) studies and found that while DDC significantly elevated the levels of expression of these inflammatory mediators, the apoA-I transgenic animals had markedly reduced expression." (PMID 22479476, 2012). "Thus, both TLR4 and TLR2 could participate in the sensing of abnormal levels of nutrients, especially fatty acids and in the detection of gut microflora modification in obesity." (PMID 23316186, 2012). "Therefore, TLR2 may be an important player in the perpetuation of inflammation that characterizes obesity." (PMID 19348674, 2009). "Toll‐like receptors (TLRs), especially TLR2 and TRL4, play an important role in obesity‐related inflammation." (PMID 39968210, 2025). "Key immune pathways involving TLR2, TLR3, and PD-1/PD-L1 were shown to modulate the balance between innate and adaptive immunity, with smoking, aging, diabetes, and obesity also impacting critical cytokine responses." (PMID 39456722, 2024). "According to the authors, exopolysaccharide derived from L. plantarum L-14 binds to TLR2, reduces chronic inflammation in mice fed an HFD, and has a positive effect on obesity by triggering AMPK signaling." (PMID 38719777, 2024). "We also studied the role of TLR2 and TLR4 in the development of mature onset obesity and insulin resistance by using TLR2−/− and TLR4−/−, as well as TLR2−/−-TLR4−/− mice." (PMID 36555322, 2022). "This implies that TLR2 is an important regulator of the inflammatory and metabolic pathways of HFD-induced obesity." (PMID 36501080, 2022). "In conclusion, our data show that the AT SRA1 expression correlates with TLRs-3,4,7,9, MyD88, NF-κB, and IRF5 expression in individuals with T2D and with TLR2, IRAK1, and IRF3 expression in individuals with obesity." (PMID 36552771, 2022). "Our findings prove that TLR2 negatively regulates adipocyte differentiation and that TLR2 and TLR4 play opposing roles in the development of mature onset obesity in mice." (PMID 36555322, 2022). "In fact, TLR2−/−TLR4−/− mice are undistinguishable from WT mice with respect to insulin resistance and obesity phenotypes." (PMID 36555322, 2022).
Obesity (continued). "TLR2 and TLR4 are key markers of inflammation in the context of obesity since they bind microbial products as LPS or peptidoglycan (PGN) and fatty acids (FAs) that are present at higher levels in the plasma of obese subjects." (PMID 36010611, 2022). "By contrast, other studies reported increase TLR2 and TLR4 gene expression especially in the adipose tissue of diet-induced obesity in mice." (PMID 34083551, 2021). "Of note, TLR4 expression is enhanced significantly in adipose tissue macrophages during obesity and TLR4/TLR2 expression was found to be significantly higher in M1 compared to M2 macrophages." (PMID 32806763, 2020). "The expression of IL-10, CD36, TLR2, and HSP70 (stress and/or obesity-related genes) was significantly upregulated in overfed fish." (PMID 32854279, 2020). "Among the TLR family members, TLR2 and TLR4 are considered important regulators of metabolic inflammation during the development of obesity and related comorbidities." (PMID 31936430, 2020). "Knocking out TLR2 and TLR4 can prevent diet-induced obesity and insulin resistance through inflammatory signaling pathways." (PMID 31952471, 2020). "Our data show strong positive correlations between adipose IRF5 gene expression and that of TLR2, TLR7, TLR8, TLR9, MyD88, IRAK-1, and IRF3 in obesity." (PMID 31718015, 2019). "In conclusion, the present study suggests that a compensatory genetic interaction between TLR2 and TLR4 contributes to the prenatal LPS stimulation-induced hyperlipidemia and lipid overload-induced obesity." (PMID 31507457, 2019). "Accordingly, the expression of TLR2 and TLR4, as well as the activity of NF-κB, are increased in obese and type 2 diabetic humans, and in rodent models of HFD-induced obesity." (PMID 29186929, 2017). "During the progression of obesity, LC n-3 PUFA antagonize AT inflammation by antagonizing LPS- and SFA-induced TLR2/4 signaling in adipocytes and immune cells." (PMID 29186929, 2017). "In summary, we found deregulated expression of TLR6 with a concomitantly activated downstream TLR2/TLR6 activity towards the expression of pro-inflammatory cytokines in peripheral blood cells and in hepatocytes from obesity-related NAFLD patients." (PMID 27834919, 2016). "FFA is also an endogenous ligand for TLR2 and TLR4 which play important roles in the pathogenesis of noninfectious, inflammatory diseases of host deregulation such as obesity." (PMID 22675336, 2012). "Previously, it has been shown an increase in protein expression of TLR-2, MyD88, and TRAF6 as well as NF-κB in human adipose tissue in states of obesity and diabetes mellitus type 2." (PMID 21266050, 2011). "Adipocytes express both TLR2 and TLR4 and the expression of these receptors is upregulated in obesity." (PMID 21356117, 2011). "Therefore, targeting TLR2 may contribute to prevention of obesity-induced inflammation." (PMID 19348674, 2009). "An understanding of the role of TLR2 and its interactions with other receptors in the adipocyte may yield significant insights into the regulation of inflammation in obesity and may help in the search for new therapeutic targets against obesity-induced impairment of insulin signaling." (PMID 19348674, 2009). "Therefore, this may implicate TLR2 in phenomenon of obesity-induced adiponectin resistance." (PMID 19348674, 2009). "There were some sex differences in the expression of monocyte activation markers: in children with obesity, expression (MFI) of CCR2, CD11b, CD11c, TLR2 and TLR4 were higher in females than males indicating that monocytes in female children with obesity have a more pro-inflammatory phenotype." (PMID 38741712, 2024). "This theory was followed by a series of studies on mice and cell cultures indicating that the downregulation of Toll-like receptor 2 (TLR2) and Toll-like receptor 4 (TLR4) in diet-induced obesity improves adipocyte differentiation and insulin sensitivity in mice." (PMID 37446161, 2023).
Obesity (continued). "SRA1 expression associated with TLR2, IRAK1, and IRF3 expression only in individuals with obesity, regardless of diabetes status." (PMID 36552771, 2022). "Another research found that the protein Amuc_1100 derived from the outer membrane of A. muciniphila maintained the integrity of the intestinal barrier by interacting with toll-like receptor 2 (TLR2), thereby alleviating obesity and insulin resistance in HFD-fed mice." (PMID 35242721, 2022). "Regarding expression of TLRs, their downstream signaling mediators and IRFs, adipose expression of TLR2 (p = 0.018), TLR3 (p = 0.010), TLR8 (p = 0.048), IRAK1 (p = 0.047), and IRF5 (p = 0.016) was significantly higher in participants with obesity compared to NW participants." (PMID 36552771, 2022). "Enhanced S100β levels, suggestive of reactive gliosis, have been shown during absence of TLR4 or TLR2 signaling, enteric dysbiosis, diet-induced obesity, impaired mitochondrial respiration, mechanical nerve injury." (PMID 33923250, 2021). "The absence of Tlr2 alleviates insulin resistance and decreases levels of molecular markers of inflammation in obesity." (PMID 34834553, 2021). "A recent study unveiled that toll-like receptors TLR2 and TLR4 in islets may integrate inflammatory signals in diet-induced obesity to attenuate adaptive changes that govern β-cell replication." (PMID 33817571, 2021). "Moreover, TLRs, especially TLR2 and TLR4, induce insulin resistance, which is crucial in the pathogenesis of obesity." (PMID 32429330, 2020). "The lack of any measurable differences in body weight or body fat gain seen in Cd14−/− mice, compared to Wild-Type or Tlr4−/− mice, suggests that TLR2 signalling is unlikely to have a role in diet-induced obesity." (PMID 30353127, 2018). "Additional to organelle stress, Toll-Like receptors, including TLR2 and TLR4 have received attention for their roles in the development of obesity and insulin resistance, although the mechanisms by which they contribute still remain unclear." (PMID 28883915, 2017). "Saturated fatty acids stimulate TLR2, promoting insulin resistance through the unfolded protein response (UPR) and nitric oxide (NO) production, demonstrating a connection between TLR2 and obesity." (PMID 23880853, 2013). "It has been demonstrated to interact with Toll-like receptor 2 (TLR2) and slightly promote glucagon-like peptide-1 (GLP-1) production via L cells, thereby enhancing intestinal microecology and improving metabolic outcomes in murine models of obesity and diabetes." (PMID 40028328, 2025). "It has been also documented that that TLR2/4-dependent inflammatory activation and lipid oxidation in the lung triggered by PM2.5 exposure can spill over systemically, leading to metabolic dysfunction and weight gain, as well as a transgenerational transmission of obesity developmental programming." (PMID 33652701, 2021). "However, obesity and sex hormones showed opposite influences on surface expression of TLR2 and TLR4, but not on their gene expression, pointing to regulatory posttranscriptional mechanisms." (PMID 31936430, 2020). "Multiple TLRs, including TLR2, TLR3, TLR4, TLR5, TLR8, TLR9, and TLR10, have been indicated in the regulation of PAMPs from gut microbiota and DAMPs from metabolic stress and tissue damage, which initiate the inflammatory responses contributing to the development of obesity-related chronic diseases." (PMID 31582899, 2019). "To test the impact of pregravid obesity on the functional responses of innate immune cells, we measured cytokine, chemokine, and growth factor production from PBMC following overnight stimulation with TLR2 (Pam3CSK4), 3 (PolyI:C), 4 (LPS), 6 (FSL-1), 7 (Imiquimod), and 9 (ODN2216) ligands." (PMID 30131724, 2018). "Thus, deregulated TLR6 expression may potentiate TLR2-mediated liver inflammation in NAFLD pathogenesis, and also serve as a potential peripheral biomarker of obesity-related NASH." (PMID 27834919, 2016).
Obesity (continued). "Whereas the changes in TLR2/TLR4 expression in the adipose tissue are regarded as important actors in metabolic inflammation, the changes in the adipose tissue expression of endocytic TLR8 in obesity/T2D remain unclear." (PMID 27980459, 2016). "Indeed, particular TLRs such as TLR2 and TLR4 link inflammation to metabolism and obesity." (PMID 25689154, 2015). "However, with the methionine and choline-deficient (MCD) diet model mouse, which develops steatosis with severe hepatitis and fibrosis without obesity, TLR2 knockout resulted in progression of NASH." (PMID 24786095, 2014). "While recently one report stated that mRNA levels of TLR2, TLR6, and TLR7 are decreased in mice fed a high-fat diet, other studies provide evidence that TLR1-9 and TLR11-13 are up-regulated in murine adipose tissue following obesity-induction by a high-fat diet." (PMID 24432024, 2014). "In particular, TLR2 and TLR4 are highly expressed in macrophages and adipose tissue and can be activated by (saturated and oxidatively modified) fatty acids, elevated during obesity, resulting in NFκB-dependent differentiation with enhanced secretion of pro-inflammatory cytokines (e.g. TNFα)." (PMID 22272346, 2012). "Therefore, because TLR2 and TLR4 are activated in adipose tissue in obesity, the induction of SLPI in adipose tissue during obesity may be influenced by the activation state of the TLRs." (PMID 21356117, 2011). "Despite the current study being the first to assess the link between TLR2 (Arg753Gln) SNP and obesity metaflammation, it was not free from limitations that included the relatively small sample size that was disproportionate between the obesity group and controls." (PMID 39837875, 2025). "Specifically, obesity leads to increased intestinal permeability and lipids, while elevated levels of circulating gut bacteria and free fatty acids may promote pro-inflammatory macrophage infiltration by binding to pattern recognition receptors such as TLR4 and TLR2." (PMID 39497804, 2024). "Mechanistically, TLR2, NOX2 and MyD88 have been proposed to modulate the positive and negative impact of MMe macrophages in HFD-induced obesity." (PMID 37153549, 2023). "Mice lacking TLR2 and TLR4 genes do show however that TLRs are involved in the development of obesity." (PMID 28883915, 2017). "Also, activation of TLR2 (Pam3Cys) or TLR4 (LPS), which has been shown to occur in obesity, has no outspoken effect on glycerol secretion." (PMID 32849273, 2020). "However, sex, sexual steroids, and obesity did not influence TLR2 and TLR4 expression postprandially, despite obese subjects, chiefly men, showing higher fasting TLR2 levels than non-obese individuals." (PMID 31936430, 2020). "Interestingly, in mice, the absence of TLR2 and TLR4 from the plasma membrane protects against obesity and IR, which generated a lot of interest in the TLRs as possible therapeutic targets in the fight against obesity and IR." (PMID 37513660, 2023).
asthma (107 papers, 2005 to 2025). "Specific polymorphisms, such as TLR2 rs3804100, are associated with allergic asthma, whereas TLR2 rs4696480 shows a significant link to asthma susceptibility." (PMID 40672946, 2025). "The relevance of the TLR2 rs4696480 polymorphism established in atopic dermatitis raises the possibility of a similar effect in asthma, potentially influencing IgE levels via FCER1A expression regulation." (PMID 40672946, 2025). "Regarding asthma, TLR2, TLR4, TLR7, TLR8, and TLR9 polymorphisms have been elucidated by their implication in allergic and asthma pathways and are also related to allergic and asthma exacerbations." (PMID 37920579, 2023). "The variation in the Toll-like receptor 2 genes (TLR2-16934A > T) among individuals with AD and total IgE levels ≥ 106 IU/mL is linked to the presence of asthma, allergic conjunctivitis, or a family history of atopic diseases." (PMID 38256282, 2023). "This study is the first to report the association between TLR2 rs7656411 and AR, although this SNP has been previously associated with asthma in the Chinese population." (PMID 37426425, 2023). "Studies using animals with TLR2 knockout have shown that TLR2 is involved in the development of asthma and is associated with the TH2 immunological pathway." (PMID 37760825, 2023). "To assess the correlation between intestinal flora and asthma inflammatory factors, we performed a linear correlation analysis between inflammatory factors and genera closely associated with TLR2 and TLR7 receptor expression in the intestinal flora." (PMID 36636604, 2023). "Smit et alreported that TLR2 rs3804099 was associated with an increased risk for asthma in family-based analyses." (PMID 36386838, 2022). "The polymorphism of the toll-like receptor 2 genes (TLR2-16934A > T) in patients with AD with total IgE ≥ 106 IU/ml is associated with asthma, allergic conjunctivitis, or atopic family history." (PMID 36465933, 2022). "The risk of having doctor-diagnosed asthma increased with increasing PM2.5 levels in children with at least one copy of the TLR2 rs4696480 A allele (OR 2.0 (95% CI 1.2 to 3.1) for an interquartile range increase in exposure)." (PMID 32411804, 2020). "TLR2 gene polymorphisms have been associated with asthma, and high TLR2 expression has been shown in farming children in Europe." (PMID 30140427, 2018). "TLR2 deletion blocks the development of asthma, but cannot block the proinflammatory effect caused by B7-H3." (PMID 28094276, 2017). "Another study found a reduced risk of doctor-diagnosed asthma in adults with a T-allele of the TLR2-rs4696480 SNP27." (PMID 28262750, 2017). "In this study, TLR2-deficient mice were sensitized and chanllenged to induce asthma with OVA, and recombinant mouse B7-H3 was administrated in one group." (PMID 28094276, 2017). "Concentrations of OVA-IgE in plasma were also significantly lower in the TLR2-deficient mice group (110.35 ± 13.61 ng/ml) with asthma compared with that of wild-type group (P = 0.025)." (PMID 28094276, 2017). "But there was no significantly difference of B7-H3-positive cells in lung between the TLR2-deficient mice group with asthma and the wild-type group." (PMID 28094276, 2017). "The analysis revealed a significant association between the TLR2 +596 CT genotype and asthma in the Puerto Rican population with an OR of 3.24, p 0.023." (PMID 27495363, 2016). "Only the TLR2 +596 SNP was found to be significantly associated to asthma (OR = 3.24 for CT, 2.71 for TT) and particularly to females." (PMID 27495363, 2016). "In this regard, polymorphisms in TLR2 have been associated with asthma, implicating the importance of intact TLR signaling pathways." (PMID 27309732, 2016). "The TLR2 +596 SNP (genotypes: CT and TT) was associated to asthma within the Puerto Rican population as demonstrated among French atopic subjects carrying the allele C, while non-atopic subjects revealed a positive but not significant association." (PMID 27495363, 2016).